C19orf12 (chromosome 19 open reading frame 12)
Description:
Adipocyte protein localized at lipid droplet-mitochondria contact sites that governs lipid storage through regulation of mitochondrial fatty acid metabolism.
Synonyms: MGC10922; DKFZP762D096; NBIA4; MPAN; NBIA3; SPG43
Tractability: Antibody: UniProt predicts a signal peptide or a membrane-spanning region. PROTAC: ubiquitination databases record sites on it; its protein half-life has been measured.
Gene: Protein-coding gene on chromosome 19 (29,698,937 to 29,716,060, reverse strand). Ensembl gene ENSG00000131943.
Subcellular location: Mitochondrion; Mitochondrion membrane; Endoplasmic reticulum; Cytoplasm, cytosol; Lipid droplet
Subcellular location (Human Protein Atlas): Cytosol
Gene Ontology:
Biological process: apoptotic process; autophagy; lipid metabolic process; mitochondrial calcium ion homeostasis; response to oxidative stress
Cellular component: cytosol; endoplasmic reticulum; lipid droplet; mitochondrial membrane; mitochondrion
Genetic constraint (gnomAD): Loss-of-function variants: 2 observed, 11.09 expected, observed/expected ratio (o/e) 0.18, 90% interval 0.073 to 0.57. The upper end of that interval is the gene's LOEUF score, 0.57, which puts it in group 2 of 6, group 1 being the genes least tolerant of losing a copy. Missense variants: 156 observed, 197.16 expected, observed/expected ratio (o/e) 0.79, 90% interval 0.69 to 0.9. Synonymous variants: 89 observed, 88.36 expected, observed/expected ratio (o/e) 1.01, 90% interval 0.85 to 1.2.
Gene-disease validity (ClinGen):
ClinGen rates the evidence that C19orf12 causes each of these diseases.
neurodegeneration with brain iron accumulation 4 (autosomal recessive): Definitive.
neurodegeneration with brain iron accumulation 4 (autosomal dominant): Moderate.
Homologues: Orthologues: chimpanzee C19H19orf12 (99% identical), macaque C19H19orf12 (95% identical), pig C19orf12 (86% identical), rabbit C19orf12 (85% identical), rat C1h19orf12 (83% identical), dog C19orf12 (82% identical), mouse 1600014C10Rik (82% identical), tropical clawed frog c4h19orf12 (66% identical), zebrafish C18H19orf12 (60% identical), zebrafish C18H19orf12 (56% identical), guinea pig C19orf12 (52% identical), zebrafish C18H19orf12 (51% identical), and 2 more.
Diseases named in the same sentence as C19orf12 in open-access papers:
C19orf12 is named in the same sentence as 36 diseases in open-access papers, as found by Europe PMC text mining. Sharing a sentence is not in itself a finding about the gene and the disease. The quoted sentences say what the papers report.
Neurodegeneration (5 papers, 2014 to 2024). Progressive loss of neural cells and tissue. "Mitochondrial membrane Protein Associated Neurodegeneration (MPAN) is a rare genetic disorder due to mutations in C19orf12 gene." (PMID 33425903, 2020). "Mutations in C19orf12 have been identified in patients affected by Neurodegeneration with Brain Iron Accumulation (NBIA), a clinical entity characterized by iron accumulation in the basal ganglia." (PMID 26136767, 2015). "Based on these evidences, MPAN (Mitochondrial membrane Protein-Associated Neurodegeneration) has been proposed as acronym to refer to C19orf12-associated NBIA." (PMID 24586779, 2014). "C19orf12 is a protein of unknown function associated with the neurodegenerative disease MPAN9." (PMID 38565923, 2024). "Mutations of C19orf12 were also found in a patient with Parkinson disease and post mortem examination of the brain of one MPAN patient revealed Lewy bodies, tangles, spheroids, and tau pathology, indicating a possible overlap between NBIA and more common neurodegenerative diseases." (PMID 26136767, 2015).
Parkinsonism (4 papers, 2017 to 2025). Characteristic neurologic anomaly resulting from degeneration of dopamine-generating cells in the substantia nigra, a region of the midbrain, characterized clinically by shaking, rigidity, slowness of movement and difficulty with walking and gait. "Notably, C19orf12 mutations have been linked to Parkinson's Disease (PD), strengthening the possibility that PD is linked to defective MERCs function." (PMID 29312934, 2017).
Dystonia (3 papers, 2013 to 2025). An abnormally increased muscular tone that causes fixed abnormal postures. "Meanwhile, cases classified as “quite inconsistent” were mostly focal (n = 15) or segmental/multifocal (n = 8) dystonia and involved variants in genes typically associated with other disorders where dystonia is rarely reported, such as C19orf12, GRN, KIF1A, and PRKCG." (PMID 40533913, 2025). "Variants in movement disorder genes frequently comprising dystonia as a phenotype included recurrent variants in ADCY5, C19orf12, and SLC2A1." (PMID 40533913, 2025). "New subtypes of neuronal brain iron accumulation have been delineated and linked to mutations in C19orf12 and WDR45, while a new treatable form of dystonia with brain manganese deposition related to mutations in SLC30A10 has been described." (PMID 23757263, 2013).
neurodegeneration with brain iron accumulation (3 papers, 2015 to 2024). "The current study focuses on the Drosophila homologs of human c19orf12 gene, which is mutated in a familial neurodegenerative disorder–Neurodegeneration with brain iron accumulation (NBIA)." (PMID 38335241, 2024). "In this study, we decipher the function of the Drosophila melanogaster gene nazo, whose human counterpart–c19orf12, is mutated in a familial neurodegenerative disorder Neurodegeneration with Brain Iron Accumulation (NBIA)." (PMID 38335241, 2024).
pallido-pyramidal syndrome (3 papers, 2014 to 2020). "Mutations in C19orf12 cause other neurodegenerative disorders such as: pallido-pyramidal syndrome, hereditary spastic paraplegia phenotype 43 (SPG43) and ALS." (PMID 30744104, 2019).
Spastic paraplegia (3 papers, 2020 to 2025). Complete loss of the ability to move the lower limbs accompanied by spasticity of the lower limbs. "Variants in C19orf12 induce a progressive spastic paraplegia, optic atrophy, motor axonal neuropathy, and psychiatric problems and has been named mitochondrial membrane protein-associated neurodegeneration." (PMID 33426505, 2020). "In four patients, rare heterozygous RDVs were detected in other neurodegeneration-associated genes, such as PRKN (PD), LRRK2 (PD), PARK7 (PD), C19ORF12 (NBIA), SPG11 (Spastic paraplegia-SP/ALS), and PSAP (Metachromatic leukodystrophy-MLD)." (PMID 35752680, 2022).
Ataxia (2 papers, 2023 to 2025). Ataxia refers to impaired coordination of voluntary muscle movement. "Abnormalities of the nervous system, including neurodevelopmental abnormality (HP:0012759), ataxia (HP:0001251), seizure (HP:0001250), peripheral neuropathy (HP:0009830) etc., were present in 44% of the families reported, and the top five contributing genes were POLG, SPG7, MFN2, FXN and C19ORF12." (PMID 39423307, 2025).
breast carcinoma (2 papers, 2012 to 2017). "Taken together, our results suggest that UQCRFS1, POP4, C19ORF12, CCNE1 and C19ORF2 are overexpressed in primary breast cancers and/or breast cancer cell lines harbouring their amplification, and may constitute potential drivers of this amplicon." (PMID 22433433, 2012).
dementia (2 papers, 2022 to 2023). Loss of intellectual abilities interfering with an individual's social and occupational functions. "In our NGS study, we identified RDVs in genes which were previously associated with other neurodegenerative disorders with or without dementia, such as C19ORF12, PRKN, LRRK2, and PARK7 genes in three patients (P81, P35, P50)." (PMID 35752680, 2022).
pantothenate kinase-associated neurodegeneration (2 papers, 2013 to 2025). "In addition to the core syndromes of pantothenate kinase-associated neurodegeneration (PKAN, NBIA1) and PLA2G6-associated neurodegeneration (PLAN, NBIA2), several other genetic causes have been identified (including FA2H, C19orf12, ATP13A2, CP and FTL)." (PMID 23814539, 2013).
amyotrophic lateral sclerosis (1 paper, 2025). Amyotrophic lateral sclerosis (ALS) is a neurodegenerative disease characterized by progressive muscular paralysis reflecting degeneration of motor neurons in the primary motor cortex, corticospinal tracts, brainstem and spinal cord. "C19orf12 encodes a mitochondrial small transmembrane protein that causes a spectrum of related conditions, including mitochondrial membrane protein-associated neurodegeneration (MPAN), AR-SPG43, and amyotrophic lateral sclerosis (ALS)-like phenotypes." (PMID 41153514, 2025).
breast tumors (1 paper, 2010). "In both ovarian tumor data sets analyzed the minimal mapped region of gain incorporated the same five genes (POP4, PLEKHF1, C19orf12, CCNE1 and C19orf2), with similar overlapping regions detected in endometrial and breast tumors." (PMID 21103391, 2010).
dementia with Lewy bodies (1 paper, 2022). "As PARK7 is suggested to cause dementia with Lewy bodies (DLB), the coexistence of variants in C19ORF12 and PARK7 is assumed to contribute to the symptoms of P50." (PMID 35752680, 2022).
Insulin resistance (1 paper, 2024). Increased resistance towards insulin, that is, diminished effectiveness of insulin in reducing blood glucose levels. "Of note, C19orf12 expression is inversely correlated with factors related to adiposity and insulin resistance in human cohorts, validating the relevance of our in vitro knockdown experiments and emphasizing the clinical importance of C19orf12 in human metabolism." (PMID 38565923, 2024).
neuroblastoma (1 paper, 2025). Neuroblastoma (NB) is the most common solid, extracranial childhood tumor. "The mitochondrial phenotype was largely confirmed in SH-SY5Y neuroblastoma cells carrying a heterozygous dominant variant in the C19orf12 gene, in two fibroblast lines, and the brain parenchyma from MPAN." (PMID 40867110, 2025). "Western blottings performed in patients’ fibroblasts (p.Glu91*, p.Lys71*) or KI neuroblastoma lines (p.Pro81Trefs*9) show a strong reduction or even the complete absence of the protein, suggesting an effect of the variants on the total amount of C19orf12 protein." (PMID 40867110, 2025). "The deletion of the C19orf12 gene in the M17 neuroblastoma cell line led to changes in mitochondrial morphology associated with impaired mitochondrial respiration." (PMID 40867110, 2025).
Obesity (1 paper, 2024). Accumulation of substantial excess body fat. "In human patient cohorts, we found that C19orf12 expression in WAT was inversely correlated with obesity-associated clinical parameters, which underlies the key role of C19orf12 in human adipocyte lipid storage." (PMID 38565923, 2024).
Optic neuropathy (1 paper, 2022). "Also in “optic neuropathy”, the fourth most enriched panel in POL, the majority of pathogenic alleles came from one gene—C19orf12, with NM_031448.6(C19orf12):c.171_181del (rs515726204) being a founder mutation originating from the Polish population." (PMID 35562925, 2022).
ovarian carcinoma (1 paper, 2012). A malignant neoplasm originating from the surface ovarian epithelium. "Amplicon-dependent expression of CCNE1, together with the genes POP4, PLEKHF1, C19orf12 and C19orf2 that flank CCNE1 on this segment, was linked with primary treatment failure in ovarian cancer, possibly due to rapid repopulation of the tumor after chemotherapy." (PMID 22291905, 2012).
immune diseases (1 paper, 2022). "C19orf12 + S1PR3 is most associated with these immune cells and S1PR3 can be used as a diagnostic marker of this kind of immune diseases." (PMID 35509008, 2022). "So far, the exact cellular function of C19orf12 and its relationship with immune diseases are not clear." (PMID 35509008, 2022).
mitochondrial disease (1 paper, 2018). "Surprisingly, this included 3 genes with a literature reported function in mitochondrial metabolism, in which pathogenic variants are a well-known cause of mitochondrial disease (RRM2B, c19orf12, TAZ)." (PMID 30369941, 2018).
neurological disease (1 paper, 2018). "Out of the 7 PNF ORF proteins identified, C19orf12 protein appears to be the most well studied but within the clinical context of neurological disease." (PMID 29449571, 2018).
C19orf12 also shares sentences with these, for which no sentence is quoted: movement disorder (2 papers); tumor (2); Brain Iron Accumulation (1); cognitive decline (1); fronto-temporal dementia (1); genetic disorder (1); hereditary spastic paraplegia type 43 (1); infantile neuroaxonal dystrophy (1); metachromatic leukodystrophy (1); Motor axonal neuropathy (1); motor neuron disease (1); optic atrophy (1); ovarian tumor (1); peripheral neuropathy (1); spastic ataxia (1).